DMBX1 (diencephalon/mesencephalon homeobox 1)
Description:
Functions as a transcriptional repressor. May repress OTX2-mediated transactivation by forming a heterodimer with OTX2 on the P3C (5'-TAATCCGATTA-3') sequence. Required for brain development (By similarity).
Synonyms: MBX; OTX3; PAXB; Atx
Tractability: PROTAC: ubiquitination databases record sites on it.
Gene: Protein-coding gene on chromosome 1 (46,489,822 to 46,516,218, forward strand). Ensembl gene ENSG00000197587.
Subcellular location: Nucleus
Gene Ontology:
Molecular function: sequence-specific double-stranded DNA binding; DNA binding; DNA-binding transcription factor activity; DNA-binding transcription factor activity, RNA polymerase II-specific; RNA polymerase II transcription regulatory region sequence-specific DNA binding; sequence-specific DNA binding; DNA-binding transcription repressor activity, RNA polymerase II-specific; identical protein binding
Biological process: brain development; central nervous system development; developmental growth; negative regulation of DNA-templated transcription; regulation of transcription by RNA polymerase II; negative regulation of transcription by RNA polymerase II; regulation of DNA-templated transcription
Cellular component: chromatin; nucleus; transcription regulator complex
Genetic constraint (gnomAD): Loss-of-function variants: 7 observed, 32.28 expected, observed/expected ratio (o/e) 0.22, 90% interval 0.12 to 0.41. The upper end of that interval is the gene's LOEUF score, 0.41, which puts it in group 1 of 6, group 1 being the genes least tolerant of losing a copy. Missense variants: 460 observed, 529.51 expected, observed/expected ratio (o/e) 0.87, 90% interval 0.8 to 0.94. Synonymous variants: 222 observed, 223.54 expected, observed/expected ratio (o/e) 0.99, 90% interval 0.89 to 1.11.
Homologues: Orthologues: chimpanzee DMBX1 (99% identical), macaque DMBX1 (98% identical), pig DMBX1 (97% identical), rabbit DMBX1 (95% identical), mouse Dmbx1 (94% identical), guinea pig DMBX1 (93% identical), dog DMBX1 (93% identical), rat Dmbx1 (93% identical), tropical clawed frog dmbx1 (75% identical), zebrafish dmbx1a (72% identical), zebrafish dmbx1b (67% identical). Paralogues in human: ARX (23% identical), ALX4 (23% identical), PITX2 (23% identical), PITX1 (22% identical), PITX3 (21% identical), VSX2 (20% identical), ALX1 (19% identical), DRGX (19% identical), PAX7 (19% identical), UNCX (19% identical), ALX3 (19% identical), OTP (19% identical), and 38 more.
Diseases named in the same sentence as DMBX1 in open-access papers:
DMBX1 is named in the same sentence as 7 diseases in open-access papers, as found by Europe PMC text mining. Sharing a sentence is not in itself a finding about the gene and the disease. The quoted sentences say what the papers report.
Hydrocephalus (2 papers, 2008 to 2012). Hydrocephalus is an active distension of the ventricular system of the brain resulting from inadequate passage of CSF from its point of production within the cerebral ventricles to its point of absorption into the systemic circulation. "Homozygous disruption of the Pten or β-catenin gene in Dmbx1-expressing cells caused severe hydrocephalus and mortality during the postnatal period." (PMID 18928559, 2008). "Further investigations are needed to elucidate the pathogenic mechanisms leading to hydrocephalus in the PtenloxP/loxP; Dmbx1-Cre and β-cateninloxP/loxP; Dmbx1-Cre mice." (PMID 18928559, 2008). "The malformation of the midbrain aqueduct probably causes obstructive hydrocephalus in the β-cateninloxP/loxP; Dmbx1-Cre mice." (PMID 18928559, 2008). "Continuous expansion of soma size of Dmbx1-expressing cells presumably causes non-communicating hydrocephalus in the PtenloxP/loxP; Dmbx1-Cre mice." (PMID 18928559, 2008). "An additional sample with two events was a fetus with hydrocephalus found to have two duplication CNVs, on chromosome bands 1p33 (including the genes FAAH, DMBX1 and KNCN) and 10q11.22 (containing the genes SYT15, GPRIN2 and PPYR1), but parental samples were not available in this case." (PMID 23056206, 2012).
psoriasis (1 paper, 2016). An autoimmune condition characterized by red, well-delineated plaques with silvery scales that are usually on the extensor surfaces and scalp. "We found that CpG sites of C1orf106, DMBX1, and SIK3 mediate the genetic risk of psoriasis." (PMID 27980695, 2016).
recessive intellectual disability (1 paper, 2020). "Interestingly, we have previously argued in support of the involvement of DMBX1 in the etiology of autosomal recessive intellectual disability based on the original family and a follow up family with the same founder (NM_147192.2:c.367C>T:p.(Arg123Trp)." (PMID 33456446, 2020).
metabolism disorders (1 paper, 2021). "Based on the pseudo-temporal continuum profile, we identified the TF (ALX4, HINFP, CEBPA, CEBPB, DMBX1, MLXIPL, ONECUT1, and RBPJL) and depicted the regulated kernel genes co-networks, which were subjected to the metabolism disorders." (PMID 33462196, 2021).
DMBX1 also shares sentences with these, for which no sentence is quoted: ischemic stroke (1 paper); obstructive hydrocephalus (1); rhabdomyolysis (1).